Y_RNA (Y RNA )
Gene: Miscellaneous RNA gene on chromosome 3 (191,641,135 to 191,641,237, forward strand). Ensembl gene ENSG00000201860.
Homologues: Orthologues: chimpanzee Y_RNA (97% identical), guinea pig Y_RNA (82% identical), dog Y_RNA (76% identical), pig Y_RNA (75% identical). Paralogues in human: RNY3 (86% identical), Y_RNA (85% identical), Y_RNA (84% identical), RNY3P1 (83% identical), Y_RNA (83% identical), Y_RNA (82% identical), RNY3P9 (81% identical), Y_RNA (81% identical), RNY3P4 (80% identical), Y_RNA (80% identical), RNY3P11 (79% identical), RNY3P14 (79% identical), and 93 more.